SMYD2 (SET and MYND domain containing 2)
Diseases named in the same sentence as SMYD2 in open-access papers (continued):
Sharing a sentence is not in itself a finding about the gene and the disease.
tumor (continued). "Relative gene expression was evaluated and tumor samples were then spatially distributed according to the expression of the trios of genes: PRSS11, MTSS1, CLPTM1 and PRSS11, MTSS1, SMYD2." (PMID 18601734, 2008). "Contrary to previous in vitro studies, we observed that SMYD2 depletion has no significant impact on cell proliferation and primary tumor growth." (PMID 38296970, 2024). "SMYD2 is a protein that takes part in the epigenetic modifications of the tumor suppressor gene and affects tumor transcription regulation by promoting nonhistone protein methylation." (PMID 37971632, 2023). "Likewise, baicalein inhibited tumor growth and reduced the levels of SMYD2 and RPS7 in the tumor tissues of xenografted mice." (PMID 35955525, 2022). "The SET and MYND domain-containing protein 2 (SMYD2) catalyzes the lysine methylation of histone and non-histone proteins to regulate multiple biological processes in tumor progression." (PMID 35022391, 2022). "On day 10, the volume of transplanted tumor began to decrease in the SMYD2 knockdown group, but there was no statistical significance." (PMID 35432530, 2022). "Due to the critical role of glutamine metabolism in tumor progression, we investigated whether GLS1 was the downstream effector of SMYD2." (PMID 36611819, 2022). "Tumor cells heavily depend on SMYD2, unlike normal cells, justifying the SMYD2 inhibitors’ high therapeutic potential." (PMID 35884603, 2022). "Inhibition of SMYD2 with SMYD2 knockdown or AZ505 dramatically inhibited the proliferation, migration, and invasion ability of GLC-82 and SPC-A1 cells and remarkably reduced tumor growth in mice." (PMID 33935284, 2021). "Whereas no obvious difference was found between high and low SMYD2 groups in other aspects, such as patient age and tumor grade." (PMID 31548876, 2019). "To further elucidate the role of SMYD2 in CDDP resistance of NSCLC cells, we next assessed the effect of inhibition or knockdown of SMYD2 on cell migration and tumor sphere formation, which are considered as the crucial characteristics of CDDP resistant NSCLC cells." (PMID 31106145, 2019). "Tumor expression of PRSS11, MTSS1, CLPTM1 and SMYD2, was evaluated by real time PCR." (PMID 18601734, 2008). "Data from Expressed Sequence Tags suggest that Smyd2 is expressed in a wide range of normal, tumor, and diseased tissues (data not shown)." (PMID 16805913, 2006). "Pathway enrichment analysis illustrated that knockdown of SMYD2 might influence several signaling pathways, including the apoptotic pathway, focal adhesion pathway, and ECM–receptor interaction pathway, which are all related to tumorigenesis and tumor progression." (PMID 33935284, 2021).
infection (4 papers, 2017 to 2025). The state of being infected such as from the introduction of a foreign agent such as serum, vaccine, antigenic substance or organism. "The identification of the H. pylori-SMYD2 axis provides novel mechanistic insights into infection-associated GC development." (PMID 40777131, 2025). "Meanwhile, SMYD2 expression was also increased at different time points after infection with H. pylori." (PMID 40777131, 2025). "We detected SMYD2 expression after infection with H. pylori and found that SMYD2 expression was remarkably increased with H. pylori infection in different MOIs and different time points." (PMID 40777131, 2025). "The results showed that SMYD2 expression was significantly up-regulated after infection with H. pylori at different MOIs." (PMID 40777131, 2025). "We detected SMYD2 expression after H. pylori strains (26695 and 11637) infection in AGS and MKN-45 cells." (PMID 40777131, 2025).
kidney disease (4 papers, 2019 to 2024). "SMYD2 is not only upregulated in several renal diseases and mediates renal injury and fibrosis, but is also closely connected to a variety of metabolic disorders." (PMID 39457592, 2024). "Currently, the role of SMYD2 in other kidney diseases remains to be reported." (PMID 31866860, 2019).
metabolic disease (2 papers, 2022 to 2024). A congenital disorder (due to inherited enzyme abnormality) or acquired (due to failure of a metabolically important organ) disorder resulting from an abnormal metabolic process. "Energy metabolism reprogramming is a vital influencer of RTC survival, and SMYD2 is a histone methylation transferase that has been extensively implicated in various metabolic disorders." (PMID 39457592, 2024).
SMYD2 also shares sentences with these, for which no sentence is quoted: cardiovascular disease (4 papers); colorectal adenocarcinoma (2); head and neck carcinoma (2); head and neck squamous cell carcinoma (2); kidney injury (2); pancreatic adenocarcinoma (2); acute myeloid leukemia (1); adenocarcinoma (1); autoimmune disease (1); brain cancer (1); cardiac disease (1); Cerebral ischemia (1); cervical squamous cell carcinoma (1); colon adenocarcinoma (1); colon adenoma (1); cutaneous T-cell lymphoma (1); diffuse large B-cell lymphoma (1); endocervical adenocarcinoma (1); gastric tumor (1); glioblastoma (1); head and neck tumor (1); heart failure (1); hemorrhage (1); ischaemia (1); lymphoid neoplasm (1); melanoma (1); myelodysplastic syndrome (1); neurological disorders (1); non-alcoholic steatohepatitis (1); oncocytoma (1).
A further 10 diseases each share a sentence with SMYD2 in 1 paper.